RNU6-977P (RNA, U6 small nuclear 977, pseudogene)
Gene: Small nuclear RNA gene on chromosome 12 (83,021,890 to 83,021,992, forward strand). Ensembl gene ENSG00000252220.
Homologues: Orthologues: chimpanzee U6 (99% identical), macaque U6 (90% identical), pig U6 (66% identical). Paralogues in human: RNU6-21P (80% identical), RNU6-1060P (79% identical), RNU6-24P (79% identical), RNU6-26P (79% identical), RNU6-767P (79% identical), RNU6-890P (79% identical), RNU6-949P (79% identical), RNU6-1011P (78% identical), RNU6-1082P (78% identical), RNU6-112P (78% identical), RNU6-1158P (78% identical), RNU6-1270P (78% identical), and 1285 more.